KLK1 (kallikrein 1)
Description:
Glandular kallikreins cleave Met-Lys and Arg-Ser bonds in kininogen to release Lys-bradykinin. (Microbial infection) Cleaves Neisseria meningitidis NHBA in saliva; Neisseria is an obligate commensal of the nasopharyngeal mucosa.
Synonyms: Klk6; KLKR; hK1
Tractability: Small molecule: a high-quality ligand is known; it belongs to a druggable protein family. Antibody: UniProt predicts a signal peptide or a membrane-spanning region. PROTAC: a small molecule that binds it is known.
Target class: Serine protease; Enzyme; Serine protease PA clan; Serine protease S1A subfamily; Protease
Gene: Protein-coding gene on chromosome 19 (50,819,146 to 50,823,787, reverse strand). Ensembl gene ENSG00000167748.
Pathways (Reactome):
Developmental Biology: Developmental Lineage of Pancreatic Acinar Cells
Metabolism of proteins: Regulation of Insulin-like Growth Factor (IGF) transport and uptake by Insulin-like Growth Factor Binding Proteins (IGFBPs)
Gene Ontology:
Molecular function: serine-type endopeptidase activity
Biological process: regulation of systemic arterial blood pressure; zymogen activation; proteolysis
Cellular component: extracellular exosome; nucleus; secretory granule
Genetic constraint (gnomAD): Loss-of-function variants: 20 observed, 23.07 expected, observed/expected ratio (o/e) 0.87, 90% interval 0.61 to 1.26. The upper end of that interval is the gene's LOEUF score, 1.26, which puts it in group 5 of 6, group 1 being the genes least tolerant of losing a copy. Missense variants: 298 observed, 350.51 expected, observed/expected ratio (o/e) 0.85, 90% interval 0.77 to 0.94. Synonymous variants: 138 observed, 142.35 expected, observed/expected ratio (o/e) 0.97, 90% interval 0.84 to 1.12.
Gene-disease validity (ClinGen):
ClinGen rates the evidence that KLK1 causes each of these diseases.
pulmonary arterial hypertension (autosomal dominant): Limited. Pulmonary arterial hypertension (PAH) is a group of diseases characterized by mean pulmonary artery pressure >20 mmHg and elevated pulmonary arterial resistance leading to right heart failure.
Homologues: Orthologues: chimpanzee KLK1 (98% identical), macaque KLK1 (92% identical), mouse Klk1 (65% identical), mouse Klk1b3 (63% identical), mouse Klk1b5 (63% identical), mouse Klk1b1 (62% identical), mouse Klk1b11 (62% identical), mouse Klk1b4 (60% identical), mouse Klk1b22 (60% identical), mouse Klk1b9 (60% identical), mouse Klk1b21 (59% identical), mouse Klk1b24 (59% identical), and 16 more. Paralogues in human: KLK2 (66% identical), KLK3 (60% identical), KLK8 (42% identical), KLK11 (41% identical), KLK14 (40% identical), KLK7 (40% identical), KLK12 (38% identical), KLK5 (37% identical), KLK4 (35% identical), TMPRSS4 (29% identical), PRSS58 (26% identical), PRSS54 (19% identical).
Diseases named in the same sentence as KLK1 in open-access papers:
KLK1 is named in the same sentence as 111 diseases in open-access papers, as found by Europe PMC text mining. Sharing a sentence is not in itself a finding about the gene and the disease. The quoted sentences say what the papers report.
Stroke (9 papers, 2015 to 2025). Sudden impairment of blood flow to a part of the brain due to occlusion or rupture of an artery to the brain. "This study highlights the risk of MetS in stroke patients and suggests a potential role for KLK1 as a mediating factor." (PMID 41322027, 2025). "The expression and activity of KLK1 are reduced in patients with cardiovascular disease, and this deficit is associated with an increased risk of acute ischemic accidents such as stroke." (PMID 41200935, 2025). "The study postulated that MetS heightens the risk of adverse outcomes in stroke patients by downregulating tissue kallikrein 1 (KLK1) levels." (PMID 41322027, 2025). "A deficiency of endogenous KLK1 has been linked with various vascular disorders, including hypertension, stroke, and myocardial infarction." (PMID 41322027, 2025). "The results indicate that among the genes associated with stroke, only KLK1 was deemed appropriate." (PMID 41322027, 2025). "Moreover, a more abundant collateral circulatory system promoted by exogenous KLK1 administration could increase the cerebral flow reserve, thereby limiting the risk of and damage from a new stroke." (PMID 39758014, 2025). "A few studies have demonstrated that intravenous KLK1 improved outcomes after experimental strokes up to 24 h after stroke induction although there is no systematic review/meta-analysis of these to assess quality and publication bias." (PMID 40069910, 2025). "The bioinformatics analysis in the current study indicates KLK1 as a potential molecule that connects various aspects of the MetS and unfavorable stroke outcomes." (PMID 41322027, 2025). "Our study reveals a U‐shaped relationship between KLK1 levels and the prognosis of both hemorrhagic and ISs, indicating that both elevated and decreased KLK1 levels can negatively impact stroke patient outcomes." (PMID 41322027, 2025). "This exploratory study indicates that MetS influences the prognosis of stroke patients through the modulation of KLK1 levels." (PMID 41322027, 2025). "Utilizing the Boruta algorithm to evaluate the influence of various factors on the prognosis of stroke patients, the results revealed that KLK1 was ranked the highest." (PMID 41322027, 2025). "Subsequently, this study delved into the relationship among MetS, KLK1 levels, and stroke prognosis in patients, drawing from an extensive multicenter prospective study conducted previously." (PMID 41322027, 2025). "This study investigated the link between MetS and stroke‐related outcomes, exploring tissue kallikrein 1 (KLK1) as a potential mediator." (PMID 41322027, 2025). "The acute and long-term effects of KLK1 both contribute to maintaining the viability of brain vascular cells in the stroke penumbra." (PMID 39758014, 2025). "Furthermore, the U‐test suggested a U‐shaped association between KLK1 levels and outcome events, indicating that both excessively high and low levels of KLK1 influenced the prognosis of stroke patients (p for U‐test = 0.014)." (PMID 41322027, 2025). "Stroke patients with MetS, exhibited lower KLK1 levels (16.8 ± 6.52 vs. 15.6 ± 6.3; p < 0.01)." (PMID 41322027, 2025). "Additionally, individuals with MetS exhibited significantly reduced levels of KLK1, and mediation analyses identified KLK1 as a potential mediator in the impact of MetS on stroke patients’ prognosis." (PMID 41322027, 2025). "Building upon these insights, our study introduces a novel hypothesis proposing that MetS impacts stroke prognosis through the downregulation of KLK1 levels." (PMID 41322027, 2025). "KLK1 acts as a mediating factor linking metabolic syndrome and stroke prognosis." (PMID 41322027, 2025). "In addition, urine-extracted KLK1 therapy has been successfully trialed in China on several hundred thousand stroke patients." (PMID 41200935, 2025). "We, therefore, suspect that the methylation of KLK1 promoter region may affect TK activity and the occurrence of stroke." (PMID 26451066, 2015).
Stroke (continued). "KLK1 could be a therapeutic target for stroke patients with metabolic comorbidities." (PMID 41322027, 2025). "In analyses stratifying patients by stroke type (ICH and IS), KLK1 demonstrated a nonlinear association with clinical outcomes for both ICH and IS." (PMID 41322027, 2025).
Hypertension (6 papers, 2020 to 2025). The presence of chronic increased pressure in the systemic arterial system. "First, the association between KLK1 and hypertension appears more evident in current investigations, as demonstrated by decreased KLK1 levels in hypertensive individuals." (PMID 41322027, 2025). "Deficiency or dysregulation of KLK1 alone can result in hypertension and is linked to atherosclerosis, as well as microvascular complications in diabetes." (PMID 41516101, 2025). "Further bioinformatics analyses indicated that obesity, diabetes, and hypertension were associated with reduced KLK1 levels (all p < 0.05)." (PMID 41322027, 2025). "Studies have shown that renal KLK1 deficiency is associated with sodium retention and hypertension." (PMID 39606015, 2024). "Indeed, hypertension has been associated with polymorphisms and deficiencies in KLK1 expression in rat models." (PMID 33256119, 2020). "By cleaving mainly low-molecular-weight kininogen to release bradykinin, KLK1 promotes vasodilation, whereby an imbalance of the KKS and the renin–angiotensin system (RAS) causes hypertension, in addition to improving microcirculatory perfusion and modulating inflammation." (PMID 41516101, 2025). "In summary, considering the MetS as a complex condition encompassing obesity, hypertension, and diabetes mellitus, it is plausible that a significant decrease in KLK1 may manifest in patients with the MetS." (PMID 41322027, 2025). "In the spleen, KLK1 protein is a biomarker candidate for hypertension." (PMID 35259090, 2022). "The KLK1 rs5516 polymorphism influences susceptibility of multiple diseases and conditions, including aortic aneurysm, thoracic aortic dissection, SLE with nephritis, and essential hypertension." (PMID 35513865, 2022).
lupus (6 papers, 2013 to 2024). "In all, our study shows that tissue Klk1 has the potential to ameliorate systemic as well as CNS lupus by reducing Type I IFN production and inflammatory response in the periphery and brain." (PMID 39337564, 2024). "To study the effects of Klk1 on microglia in lupus-prone mice, we analyzed the expression of IBA-1, a well-established marker of microglia." (PMID 39337564, 2024). "We retro-orbitally administered mouse klk1 gene-carrying adenovirus in the Murphy Roths Large lymphoproliferative (MRL/lpr) lupus-prone mice at early disease onset and analyzed immune responses and depressive-like behavior." (PMID 39337564, 2024). "Kallikrein 1 (Klk1), a widely expressed tissue Klk, is decreased in lupus patients and lupus mouse models; administration of exogenous Klk1 ameliorated lupus nephritis in mice." (PMID 39337564, 2024). "For the high KLK1 expression subgroup, we found significantly enriched pathways related to asthma, allograft rejection, systemic lupus erythematosus, type I diabetes, and the impact on intestinal immune networks for IgA production, among others." (PMID 39606015, 2024). "Using the MRL/lpr mice, a popularly used lupus-prone model, we show in a short-term study that exogenous Klk1 administration reduced depressive-like behavior, key interferon responsive genes (IRGs), and proinflammatory responses." (PMID 39337564, 2024). "Tissue Klk genes are decreased in patients with lupus, and giving exogenous Klk1 ameliorated kidney pathology in mice." (PMID 39337564, 2024). "Earlier reports have shown that antibody-induced GN in lupus-prone mice is ameliorated by exogenous administration of klk1, one of the molecules of the KKS." (PMID 29456540, 2018). "This can be one of the mechanisms by which Klk1 ameliorates the inflammatory effects of lupus." (PMID 39337564, 2024). "Furthermore, it has been demonstrated that KLK1 can protect against lupus and anti-glomerular basement membrane-specific antibody-induced nephritis in mice and humans, indicating KLK1 may be involved in autoimmunity response processes." (PMID 29348876, 2017). "Organ-specific responses vary in lupus, and for the first time, we demonstrate the effects of Klk1 in regulating IFN responses in vivo in the periphery and in the central nervous system (CNS) (neuroinflammation and behavior) in lupus." (PMID 39337564, 2024). "To understand the role of Kallikreins in candidiasis, we focused on Klk1 based on its connection to IL-17-driven diseases including EAE and systemic lupus erythematosus." (PMID 27814401, 2016). "Our study interestingly revealed that tissue Klk1 can effectively inhibit the key signaling molecules in the Type I IFN pathway, suggesting that this is a potential candidate to develop as a biologic not only for lupus but for other IFN-mediated diseases." (PMID 39337564, 2024).
Nephropathy (5 papers, 2011 to 2025). A nonspecific term referring to disease or damage of the kidneys. "In the existing studies, the use of KLK1 as a target for treating cardiovascular, cerebrovascular, and renal diseases is a current hot spot." (PMID 39116105, 2024). "Kallikrein-1 decreased 3 weeks after UUO and in the ADR-induced nephropathy model, which indicates that Kallikrein-1 is a candidate marker of glomerular injury." (PMID 25791774, 2015). "Renal kallikrein levels were markedly reduced in an aminoglycoside-induced AKI animal model, and KLK1 gene transfer protected against aminoglycoside-induced nephropathy by diminishing apoptosis and inflammation." (PMID 21679467, 2011). "KLK1 gene transfer protected against aminoglycoside-induced nephropathy, with inhibition of apoptosis and inflammation." (PMID 21679467, 2011).
prostate carcinoma (5 papers, 2017 to 2025). A carcinoma that arises from epithelial cells of the prostate gland. "So it could be speculated that KLK1 was not a predisposing factor for prostate cancer." (PMID 34007408, 2021). "In this study, KLK1, KLK4, KLK9, and KLK14 were strongly decreased in prostate cancer samples compared with controls." (PMID 33150763, 2020). "Our results point to the fact that KLK1, KLK2, and KLK14 (only in recurrent prostate cancer tissues) are underexpressed in prostate cancer tissues, while KLK3, KLK4, KLK8, and KLK9 are overexpressed in both recurrent and non-recurrent tissues." (PMID 33150763, 2020). "KLK1 was downregulated in recurrent and non-recurrent prostate cancer tissues compared with healthy samples." (PMID 33150763, 2020). "In conclusion, we propose that KLK1, KLK2, KLK3 KLK4, KLK8, KLK9, and KLK14, which are differentially expressed in prostate cancer, could be used as promising biomarkers of prostate cancer progression." (PMID 33150763, 2020).
breast carcinoma (4 papers, 2004 to 2020). "Applying the Gene Set Analysis (GSA) we found that elevated expression of HRH1, EFNB1, KLK1, NRP2, and APP was associated with the basal-like subtypes of breast cancer as predicted by the MicMa cohort." (PMID 26673618, 2016). "Some of the modulated proteins found in the present study such as haptoglobin or S100A4 have been related to CMT or human breast cancer previously, while others such as kallikrein-1 and immunoglobulin gamma-heavy chains A and D are described here for the first time." (PMID 32344524, 2020). "For example, the in vitro inhibition of KLK1 suppresses the invasiveness of breast cancer cells, and therefore it could be a defence mechanism." (PMID 32344524, 2020). "A low number of KLK1 and KLK13 mRNA messages were detectable in the MCF7 breast cancer cell line 3 h after oestradiol stimulation (16 tpm for each gene), but not in unstimulated cells (data not shown)." (PMID 14710225, 2004).
COVID-19 (4 papers, 2022 to 2025). A disease caused by infection with severe acute respiratory syndrome coronavirus 2. "Moreover, two COVID-19-related genes, Klk1 and Klk1b5, identified in the Renin-angiotensin system (RAS) in the network analysis, were upregulated by the CO diet in the duodenum." (PMID 37886485, 2023). "The induction of KNG1, KLK1, and BDKRB2 in primary nasal samples of SARS-CoV-2-positive study participants is evidence for an autocrine bradykinin effect via B2R that is triggered locally during COVID-19 disease." (PMID 35247068, 2022).
pulmonary hypertension (4 papers, 2019 to 2025). Increased pressure within the pulmonary circulation due to lung or heart disorder. "KLK1 encodes kallikrein 1, also known as tissue kallikrein, involved in the regulation of systemic blood pressure and vascular remodeling but not previously associated with pulmonary hypertension." (PMID 31727138, 2019).
diabetic nephropathy (3 papers, 2014 to 2024). "The results showed significant enrichment of the type I diabetes pathway in both the high expression groups of KLK1 and MMP10, suggesting their association with the progression of diabetic nephropathy." (PMID 39606015, 2024). "Since the kallikrein-kinin system (KKS) has been linked to cellular inflammatory process in many diseases, it is likely that KLK1 expression may mediate the inflammatory process during the development of diabetic nephropathy." (PMID 24586431, 2014). "Particularly in tubulointerstitial inflammation, KLK1 acts by activating PAR-4, providing a potential target for future diabetic nephropathy treatment." (PMID 39606015, 2024). "Together, these results suggest that up-regulation of KLK1 in tubular epithelial cells may mediate pro-inflammatory pathway and PAR activation during diabetic nephropathy and provide a new therapeutic target for further investigation." (PMID 24586431, 2014).
lupus nephritis (3 papers, 2021 to 2024). Glomerulonephritis in the context of systemic lupus erythematosus. "Klk1 mutations are also associated with lupus-nephritis in mice and humans, similar to the phenotype of Siglec-H ko mice." (PMID 34497606, 2021). "For example, genetic variants in genes expressed in the kidney (including TNFRSF1B, KLK1, KLK3, ACE, AGT, and APOL1) may result in increased susceptibility to kidney injury and, as a result, in progression to lupus nephritis." (PMID 39124752, 2024).
myocardial infarction (3 papers, 2018 to 2025). Gross necrosis of the myocardium, as a result of interruption of the blood supply to the area, as in coronary thrombosis. "Additionally, in a mouse model of myocardial infarction (MI), KLK1 gene delivery has been revealed to increase the number of resident CPCs and boost the regional blood flow and neo-vascularization in the peri-infarcted myocardium." (PMID 30544622, 2018).
nephritis (3 papers, 2017 to 2024). Inflammation of renal tissue. "Administration of tissue kallikrein (klk1) has been shown to ameliorate experimental nephritis." (PMID 39337564, 2024).
Sepsis (3 papers, 2011 to 2025). Sepsis is defined as life-threatening organ dysfunction caused by a dysregulated host response to infection. "Within the AKI group (n = 20), acute kidney injury was attributed to ischemia in 7 patients, nephrotoxins in 4, sepsis in 1, and multifactorial causes in 8; KLK1 excretion did not vary by AKI causal group (ANOVA p = 0.83)." (PMID 21679467, 2011).
acute kidney injury (2 papers, 2011 to 2023). Sudden and sustained deterioration of the kidney function characterized by decreased glomerular filtration rate, increased serum creatinine or oliguria. "A study of human acute kidney injury, the methylation status of four sites in the promoter region of cfDNA KLK1 gene was evaluated by pyrosequencing in urine and whole blood of healthy controls and acute kidney injury patients." (PMID 37858233, 2023). "In the study of human acute kidney injury, they evaluated four consecutive CpG methylations of KLK1 gene by pyrosequencing, located between − 203 and − 135 bp from the transcription start site." (PMID 37858233, 2023). "Renal kallikrein (KLK1) synthesis and urinary excretion are reportedly diminished during AKI (acute kidney injury) in animal models, and provision of kallikrein abrogates renal injury in this setting, but data in human AKI is limited." (PMID 21679467, 2011).